ABCB1 (ATP binding cassette subfamily B member 1)
Diseases named in the same sentence as ABCB1 in open-access papers (continued):
Sharing a sentence is not in itself a finding about the gene and the disease.
tumor (continued). "We, therefore, hypothesized that LPA decreases Taxol-induced accumulation of the cells in G2/M by stimulating Taxol efflux through ABCB1 (multidrug resistance gene 1), p-glycoprotein (ABCC1) or ABCG2, since these transporters account for a major portion of drug resistance in human tumor cells." (PMID 21647386, 2011). "In addition ABCB1 methylation was lower in Ki67 positive tumours (P = 0.006) and GSTP1 methylation was lower in PR negative tumours (P = 0.009)." (PMID 20056007, 2010). "Methylation at the ABCB1 or GSTP1 promoter improved overall survival probably due to prolonged availability and activity of the drug in the cell while FOXC1 methylation might be a protective factor against tumour invasiveness." (PMID 20338046, 2010). "Molecular modeling indicated strong binding affinities of ER to both ABCB1 and ABCG2 proteins, supporting the hypothesis that Erastin interacts directly with ABC transporters, modulating their activity and thereby enhancing chemotherapeutic drug retention in resistant tumor cells." (PMID 39859349, 2025). "Previous attempts were made to develop ABCB1 inhibitors for clinical use to overcome multidrug resistance, but they failed in clinical trials primarily because the trials did not limit patient selection to those whose tumours were nonresponsive to treatment due to ABC transporter overexpression." (PMID 40867257, 2025). "Adding to the fact that TGF-β incubation only marginally increased ABCB1 levels in a small fraction of the cell population, our results suggest that during mild and endogenous stimuli of tumor progression in A549 cells, ABCB1 may not confer a significant increase of tumor resistance." (PMID 37047018, 2023). "Indeed, Roessner and co-workers had found a significant correlation between ABCB1 protein expression and poor response to chemotherapy but with no clinical outcome in 21 ES tumor tissues, while two other studies had shown that ABCB1 mRNA and protein expression were not predictive for ES prognosis." (PMID 34572110, 2021). "Thus, C-MET, CDKN2A, P-glyc (ABCB1) and N-cadherin displayed significantly lower protein expression levels in HGSOC tumors corresponding to PARPis-sensitive AsPCs, while FANCF and SPRY2 showed stronger expression in the PARPis-sensitive AsPCs-matched tumor samples." (PMID 33213473, 2020). "Our study demonstrates that the ferroptosis inducer, Erastin, exhibits strong cytotoxicity against ABCB1- and ABCG2-expressing tumor cells, indicating it is not a substrate for these ABC transporters in NCI/ADR-RES and MCF-7/MXR cells." (PMID 39859349, 2025). "The top negative DEGs, including ABCB1, SPRY1, EREG, PIK3R1, SPTBN1, VIM, KDR, and others, exhibit a negative correlation with tumor purity while demonstrating a strong positive correlation with T‐cell infiltration, especially CD8+ T cells." (PMID 40567015, 2025). "Our findingsrevealed that flunarizine did not affect ABCB1 and ABCG2 transportactivity.Consistent with these findings, flunarizine also did not appreciablyaffect the plasma concentration and tumor accumulation of gefitinibin the PDX animal study." (PMID 37854628, 2023). "Transfection of ABCB1 shRNAs showed no obvious inhibitory effects of NSCLC xenografts in nude mice, however, both the volume and tumor weight of the subcutaneous transplanted tumor decreased significantly with cisplatin treatment." (PMID 30718500, 2019). "In accordance with these results, we suggest that pharmacokinetic behavior and tumor treating abilities of purvalanol A will not be affected by ABCG2 and/or ABCB1." (PMID 24116053, 2013). "Note that ABCB1 and ABCG2 gene expression from baseline (untreated) cell line tumor xenografts was used for this analysis and not the cell line gene expression data." (PMID 23524533, 2013).
tumor (continued). "In this context, it may be more straightforward to develop novel drugs which are not transported by P-glycoprotein/ABCB1 and therefore bear the potential to kill multidrug-resistant tumor cells with similar efficacy to otherwise drug-sensitive cells." (PMID 40723843, 2025). "Although ABCG2 is higher in GBM6R, available data suggest it is unlikely to explain the phenotype: in GBM cells ABCB1 dominates intracellular TMZ efflux, while ABCB1/ABCG2 chiefly restrict brain entry at the BBB—an exposure effect that cannot account for within-tumor GBM6 vs GBM6R differences." (PMID 41271669, 2025). "Among our ACC PDXs, there was considerably lower surface ABCB1 expression in POBNCI_ACC004, which had initial complete responses to ADCT-701, compared to both 164165 and 592788, which had partial but no complete anti-tumor responses to ADCT-701." (PMID 39416174, 2024). "In our study, micro-vessels could not be isolated; therefore, the measured ABCB1 and ABCG2 levels represented membrane-bound transporters of all cell types present in the sample (e.g., micro-vessels, glia cells, neurons and tumor cells)." (PMID 31832814, 2019). "There was a trend for the absence of methylation at ABCB1, FOXC1, PPP2R2B, and GSTP1 in both the basal-like and normal-like tumours, while IGF2, MLH1 and PTEN were hypomethylated in the basal-like tumours but not in the normal-like tumours." (PMID 20338046, 2010). "The average expression level of the ABCA2 (p = 0.000), ABCB1 (p = 0.000), and ABCG2 (p = 0.001) genes was statistically significantly higher in patients with diagnosed tumor cell infiltration into fat tissue compared to patients without tumor cells in the fat tissue." (PMID 36674773, 2023). "Moreover, MARCKS and ABCB1 expression were inversely correlated in six CRC tumor samples with reduced or absent MARCKS expression and in adjacent normal tissue: Normal tissue showed high MARCKS and low ABCB1 expression and tumor tissue displayed low MARCKS and high ABCB1 expression." (PMID 32056006, 2020).
infection (18 papers, 2008 to 2025). The state of being infected such as from the introduction of a foreign agent such as serum, vaccine, antigenic substance or organism. "The findings that ABCB1 SNPs are associated with H. pylori infection are important, as this infection is found in approximately 60% of the world population." (PMID 31948121, 2020). "Although lacking in exact mechanisms, these studies demonstrate that pathogens have coevolved ways to specifically target ABCB1, suggesting that host ABCB1 proteins may directly transport bacterial peptides or toxic compounds out of the gut epithelia during pathogenic infection." (PMID 38497255, 2024). "For instance, patient PKTx2’s heterozygosity for ABCB1 and ABCC2 variants, associated with tacrolimus metabolism and acute cellular rejection, likely contributed to the patient’s post-transplantation infection complications." (PMID 40126245, 2025). "We also identified two ABCB1 proteins that were upregulated in M. sextelata following infection with P. penicillatus." (PMID 34925269, 2021). "The pro-inflammatory cytokines are also involved in pathways that can enhance expression of ABCB1 gene thus regulating the efflux mechanisms to protect the host against deleterious mechanisms of infection." (PMID 28422980, 2017). "Differences in placental Abcb1 (P-gp encoding gene in the human) and Abcg2 (BCRP) mRNA expression-associated with infection and inflammation have been previously reported in human placenta." (PMID 23762418, 2013). "RT-qPCR analyses confirmed that T3 treatment significantly stimulated the expression of ABCB1 and ABCG2 mRNA in both the control-infection and TRα1 GOF conditions at all time points." (PMID 38693105, 2024). "Following infection at 10 dpi, six of the DEGs were immune genes (GAL1, GAL2, GAL7, ABCB1, LEPR and SNED1) and two were involved in NOD-like receptor signaling pathway (K60 and HSP90B1), all were upregulated in expression in line 63 birds." (PMID 31578366, 2019).
hematological malignancies (13 papers, 2016 to 2025). "Genetic variants of ABCB1 were studied in hematological malignancies, a broad variety of conclusions regarding their function was observed but their true clinical impact is still under debate." (PMID 34066083, 2021). "The aim of this investigation was to determine the impact of ABCB1 polymorphism, BMI, age and drug co-administration on safety and efficiency of posaconazole oral suspension treatment in children with hematological diseases." (PMID 31741622, 2019). "In summary, only two retinoids, ATRA and 9-cis-retinoic acid, have been evaluated for their impact on ABC transporters (exclusively ABCB1) in hematological malignancies, most commonly in leukemic cell models." (PMID 41303640, 2025). "P-glycoprotein (P-gp), a transmembrane efflux pump encoded by the ABCB1/MDR1 gene, is a major contributor to multidrug resistance in hematological malignancies." (PMID 40429842, 2025). "Here, we studied the association between SNPs of MTHFR and ABCB1 and MTX-related toxicity in 157 adult Chinese patients diagnosed with hematological malignancies." (PMID 35004279, 2021). "The aim of this study was to determine the impact of ABCB1 polymorphism, BMI, age and drug co-administration on safety and efficiency of posaconazole (PCZ) oral suspension treatment in children with hematological diseases." (PMID 31741622, 2019). "We conclude that genotyping of MTHFR and/or ABCB1 polymorphisms prior to treatment, MTHFR 677C>T particularly, is likely to be potentially useful with the aim of tailoring HDMTX therapy and thus reducing toxicity in patients with hematological malignancies." (PMID 34744734, 2021). "ABCB1 polymorphism has no impact on the efficiency and safety of posaconazole treatment in children with hematological malignancies." (PMID 31741622, 2019). "However, several studies have also investigated the role of retinoids in relation to ABC efflux transporters across various types of hematological malignancies due to the confirmed elevated gene or protein expression of these transporters, especially ABCB1, in both leukemia and lymphoma cells." (PMID 41303640, 2025). "Five-cyano-6-phenylpyrimidin derivatives containing an acylurea moiety demonstrated efficacy in inhibiting P-glycoprotein ABCB1, a leading member of ABC transport proteins found to be widely overexpressed in human solid tumors and hematologic malignancies." (PMID 38659591, 2024). "In conclusion, we identified an important influence of the SNPs of ABCB1 and MTHFR on MTX-related hematopoietic toxicity in adults with hematological malignancies." (PMID 35004279, 2021). "Here, we studied the relation between SNPs of MTHFR and ABCB1 and MTX-related toxicity in 157 adult Chinese patients diagnosed with hematological malignancies." (PMID 35004279, 2021). "First, we wanted to verify whether there is a reciprocal relationship between the gene expression of ABCB1 and ADGRL1, which we found in the AML cell lines SKM-1 and MOLM-13 in samples from patients with hematological malignancies." (PMID 34298843, 2021). "Thus, our present research aimed to study the influence of SNPs of ABCB1 and MTHFR on MTX-related toxicity in adult Chinese patients diagnosed with hematological malignancies." (PMID 35004279, 2021).
adenocarcinoma (11 papers, 1992 to 2025). A common cancer characterized by the presence of malignant glandular cells. "The ABCB1-modulating activity of the compounds was assessed by rhodamine 123 accumulation assay on the doxorubicin resistant, ABCB1 expressing Colo 320 human adenocarcinoma cell line." (PMID 36839934, 2023). "Such a stimulation was also observed in ABCB1-overexpressing human adenocarcinoma cells (LoVo/Dx) incubated in the presence of other flavonoid compounds—baicalein and luteolin." (PMID 34361789, 2021). "This suggested that the transport activity of ABCB1 was not likely to be responsible for the observed Dox resistance of human adenocarcinoma cells." (PMID 34361789, 2021).
myopathy (8 papers, 2015 to 2025). A disease of the muscle in which the muscle fibers do not function properly. "In detail, the C allele in the T521C SNP of the SLCO1B1 gene and the T allele in the C1236T SNP of the ABCB1 gene exhibit elevated serum CK levels and a higher risk of simvastatin- and rosuvastatin-induced myopathy." (PMID 29296187, 2017). "ABCB1 is important to the metabolism of colchicine, so we speculated that it was possible that colchicine myopathy patients may have a particular genotype that is associated with this side effect." (PMID 31178824, 2019). "Other SNPs associated with myopathy are the polymorphisms in the ABCB1 and ABCG2 genes." (PMID 30050433, 2018). "However, significant heterogeneity was present in all the four genetic models of the association of ABCB1 C3435T with myopathy." (PMID 26438079, 2015). "The evidence from the meta-analysis demonstrated that the ABCB1 C3435T polymorphism may represent a pharmacogenomic biomarker for predicting treatment outcomes in patients on statins and that statin treatment for more than 5 months can increase the risk of myopathy." (PMID 26438079, 2015). "Transporter-dependent drugs are affected by PXR-induced expression of MDR1 (ABCB1) and MRP2 (ABCC2), regulating the enterohepatic circulation and biliary excretion of digoxin, as well as the hepatic concentration and myopathy risk of statins (via OATP1B1 transport)." (PMID 41368631, 2025). "SNPs related to myopathy, like the SLCO1B1, ABCB1, and ABCG2 gene polymorphisms, could be taken into account when considering combined treatment with statins." (PMID 30050433, 2018). "When the three eligible studies were pooled, the association between statin-related myopathy and the ABCB1 C3435T variation was not significant." (PMID 26438079, 2015).
neurodegenerative disease (7 papers, 2012 to 2025). A disorder of the central nervous system characterized by gradual and progressive loss of neural tissue and neurologic function. "However, it remains to be tested if agonists of the pregnane X receptor (PXR) that induce ABCB1 expression have a favorable induction/repression profile on transporters and receptors also involved in pathogenesis of neurodegenerative diseases." (PMID 31417399, 2019). "Thus, neuro-inflammatory cytokines affect the expression and function of ABCB1, suggesting that neuro-inflammation in neurodegenerative diseases, including AD, may alter ABCB1 expression, although this remains to be determined." (PMID 29973883, 2018).
neurological diseases (6 papers, 2013 to 2026). "The ABCB1 gene has been found to be associated with treatment resistance in many of the neurological diseases which have been studied thus far." (PMID 23717663, 2013). "In humans, it may induce neurological disorders, particularly in individuals with mutations in the ABCB1 gene." (PMID 41901641, 2026). "A haplotype analysis within ABCB1 performed, i.a., in neoplastic and neurological diseases turned out to be a useful tool in terms of evaluation of the morbidity and the effectiveness of treatment." (PMID 29948283, 2018).
peripheral neuropathy (5 papers, 2019 to 2024). A disorder affecting the peripheral nervous system. "Genetic polymorphisms of ABCB1 (C1236T and C3435T) are associated with chronic chemotherapy-induced peripheral neuropathy in patients treated with paclitaxel." (PMID 38469410, 2024). "Otherwise, ABCB1 variants have been reported to be associated with both increased and decreased risks of peripheral neuropathy." (PMID 33326171, 2021). "A score based on age, toxic habits, cardiovascular risk factors and ABCB1 C1236T polymorphism, for a population of patients treated with paclitaxel, predicts with specificity the probability of developing chronic chemotherapy-induced peripheral neuropathy." (PMID 38469410, 2024). "- ABCB1 rs1128503 was significantly associated with grade ≥ 2 only in patients ≥ 60 years (p=0.027).- The multivariable analysis concluded a significant risk factor of this variant and age in grade ≥ 2 peripheral neuropathy (p=0.005)." (PMID 32351390, 2020).
psychiatric disease (4 papers, 2013 to 2025). "Moreover, emerging evidence suggests that ABC transporter genes, including ABCB1 and ABCB6, influence susceptibility to psychiatric disorders like MDD." (PMID 40559416, 2025).
bacterial infections (3 papers, 2016 to 2024). "LPS (lipopolysaccharide, a bacterial infection mimic) treatment increased P-gp function, with a concomitant reduction in ABCB1 levels, and no change in P-gp protein." (PMID 38737275, 2024).
blood cancer (3 papers, 2021 to 2025). "The ABCB1, ABCC1, p-AKT, p-NFκB, and NFκB levels were associated with responsiveness to eribulin in blood cancer cells, and a resistance eribulin-related target score was constructed." (PMID 36551566, 2022). "In this hematological neoplasm, it has been reported that the rate of complete remission and drug resistance are related to the function and expression of ABCB1." (PMID 34702282, 2021). "Among these molecular targets, ABCB1 (r = 0.53, p = 0.02), ABCC1 (r = 0.67, p = 0.001), p-AKT (r = 0.53, p = 0.02), p-NFκB (r = 0.80, p < 0.0001), and NFκB (r = 0.81, p < 0.0001) were associated with IC50 values for eribulin in the blood cancer cell lines." (PMID 36551566, 2022).
cardiovascular disease (2 papers, 2021 to 2024). "Other cardiovascular disease-related gene signatures, such as ABCB1 and GST, have also been proposed to be associated with susceptibility to pesticide toxicity." (PMID 39004719, 2024).
central nervous system diseases (2 papers, 2024 to 2025). "Strategies for overcoming ABCB1 action have been largely unsuccessful, which poses a tremendous clinical problem to treat central nervous system diseases." (PMID 38672482, 2024).
gastrointestinal tumor (1 paper, 2024). "TRPC5, involved in ATP-binding cassette subfamily B member 1 (ABCB1)-mediated overexpression of ABCB and cyclin D1, induces nuclear β-catenin accumulation, leading to resistance of gastrointestinal tumor cells to 5-Fluorouracil (5-FU)." (PMID 38370477, 2024).
heart disease (1 paper, 2018). "Multiple genes known or plausibly linked to heart development and post-natal heart disease were found to be differentially methylated in the blood DNA of newborns with TOF including: ABCB1, PPP2R5C, TLR1, SELL, SCN3A, CREM, RUNX and LHX9." (PMID 30212560, 2018).
hematologic cancers (1 paper, 2025). "Although hematologic cancers typically exhibit relatively low P-gp levels, post-treatment genetic instability, and clonal selection in refractory or relapsed patients enhance ABCB1 activation and P-gp overexpression." (PMID 41301675, 2025).
ABCB1 also shares sentences with these, for which no sentence is quoted: invasive breast carcinoma (7 papers); nephrotic syndrome (7); colorectal (6); systemic lupus erythematosus (5); ulcerative colitis (5); Cognitive impairment (4); gallbladder carcinoma (4); hyperlipidemia (4); laryngeal carcinoma (4); liver dysfunction (4); adenocarcinoma of the esophagus (3); benign prostate hypertrophy (3); brain diseases (3); fibrosarcoma (3); gastrointestinal disease (3); Hodgkins lymphoma (3); Huntington disease (3); oral squamous cell carcinoma (3); pancreatic adenocarcinoma (3); amyotrophic lateral sclerosis (2); angina (2); Arthritis (2); bipolar disorder (2); bladder tumors (2); cardiomyopathy (2); Central Nervous System Tumors (2); Dubin-Johnson syndrome (2); gingival hyperplasia (2); gout (2); hemorrhage (2).
A further 177 diseases each share a sentence with ABCB1 in 2 papers or fewer.